TRPM2-AS (TRPM2 antisense RNA)
Synonyms: TRPM2-AS1
Gene: Long non-coding RNA gene on chromosome 21 (44,414,588 to 44,425,272, reverse strand). Ensembl gene ENSG00000230061.
Diseases named in the same sentence as TRPM2-AS in open-access papers:
TRPM2-AS is named in the same sentence as 1 disease in open-access papers, as found by Europe PMC text mining. Sharing a sentence is not in itself a finding about the gene and the disease.
TRPM2-AS shares sentences with these, for which no sentence is quoted: Tumor (1 paper).